CD14 (CD14 molecule)
Diseases named in the same sentence as CD14 in open-access papers (continued):
Sharing a sentence is not in itself a finding about the gene and the disease.
Obesity (continued). "Metabolic characteristics of obesity and T2D in mice were not initiated by injecting LPS when CD14/TLR4 receptor was genetically deleted, showing the significant contribution of LPS/CD14/TLR4 signaling." (PMID 29167659, 2017). "Our data also showed TNF-α overexpression in CD14++CD16- classical and CD14+CD16++ non-classical monocytes from children with obesity compared to children with normal weight." (PMID 27977792, 2016). "We highlight changes in the CD14+CD16++ non-classical monocyte subpopulation in children with obesity." (PMID 27977792, 2016). "In obesity mouse models, TLR4 is known to be involved in the inflammatory response that culminates in insulin resistance and metabolic dysfunction as demonstrated when comparing wild-type to CD14−/− mice, and to TLR4−/− mice." (PMID 26161548, 2015). "Accordingly, CD14-deficient mice do not become obese on a high-fat diet and do not develop obesity-related pathologies such as insulin resistance and cardiovascular complications; these phenomena are CD14-dependent but TLR4-independent." (PMID 23898465, 2013). "Moreover, a curious negative role of CD14 in lipid accumulation, obesity, insulin resistance, and type-2 diabetes has been documented." (PMID 23898465, 2013). "Hence, the increase in expression of TGF-β observed in CD14+CD16++ non-classical monocytes from child with obesity, may be an attempt to control immune response to restore homeostasis, or tissue remodeling and fibrosis." (PMID 27977792, 2016). "The frequencies of CD14+ cells and cells expressing CD95+, independent of resistin treatment, were higher in the colostrum from diabetic mothers with obesity." (PMID 36289594, 2022). "The lack of any measurable differences in body weight or body fat gain seen in Cd14−/− mice, compared to Wild-Type or Tlr4−/− mice, suggests that TLR2 signalling is unlikely to have a role in diet-induced obesity." (PMID 30353127, 2018). "On the other hand, there was a borderline significant relation of BMI to anti-inflammatory CD14+CD16−CD163+ macrophages (P<0.03) but this correlation also disappeared after excluding subjects with obesity (data not shown)." (PMID 28394364, 2017). "The number of monocytes was only modestly higher in those with obesity, but monocyte subset analysis based on CD14 and CD16 expression showed a marked higher percentage of classical monocytes (CD14++ CD16dim) and lower percentage of non-classical monocytes (CD14dimCD16++) in subjects with obesity." (PMID 38741712, 2024).
rheumatoid arthritis (79 papers, 2007 to 2025). A chronic, systemic autoimmune disorder characterized by inflammation in the synovial membranes and articular surfaces. "A number of diseases, including Alzheimer's disease, systemic lupus erythematosus and rheumatoid arthritis, have been associated with changes in the phenotypic and functional characteristics of monocyte-derived DCs (i.e. CD14+ monocytes cultured in the presence of GM-CSF and IL-4 alone)." (PMID 21933242, 2012). "Specifically, DCs from patients with rheumatoid arthritis (RA) exhibit an increased expression of CD14 and CD16 proteins on their surface, indicating a shift towards a pro-inflammatory phenotype." (PMID 40649852, 2025). "On the other hand, in other rheumatic diseases, e.g. rheumatoid arthritis (RA), increased monocyte count (especially CD14+CD16++ subpopulation) correlates with clinical manifestations and elevated parameters of inflammation localized in peri-articular tissue." (PMID 37138886, 2023). "A phase IIa clinical trial of a human CCR2 antagonist (MLN1202) in patients with active rheumatoid arthritis found that treatment with the CCR2 antagonist reduced free CCR2 levels on CD14+ monocytes by at least 57% and up to 94%." (PMID 36566220, 2022). "This is the case of peripheral blood CD14+ mononuclear cells of subjects carrying rheumatoid arthritis and coronary artery disease, which display an increased number of MAM contact sites when compared to healthy individuals." (PMID 35372506, 2022). "Another group identified v-STEAP4 in CD14+ monocytes from patients with rheumatoid arthritis (RA) and suggested that v-STEAP4 was expressed in the nuclear fraction of THP-1 cells overexpressing v-STEAP4." (PMID 36140186, 2022). "Recent publications have shown enhanced glycolysis and OXPHOS occurring at the same time in immune cells under diverse conditions, including human natural killer cell activation and in CD14+ monocytes isolated from rheumatoid arthritis patients." (PMID 35199335, 2022). "We aimed to investigate the direct anti-inflammatory effect and anti-atherogenic effects of PNLA on activated purified CD14 monocytes from peripheral blood of patients with rheumatoid arthritis (RA) in vitro." (PMID 35614190, 2022). "This CD209/CD14+ DC population is present in the circulation of Healthy Control (HC), with increased frequency in Rheumatoid Arthritis (RA) and Psoriatic arthritic (PsA) patients." (PMID 35095831, 2021). "The expansion of CD14+CD16+ monocytes has been reported in a variety of inflammatory disorders including rheumatoid arthritis (RA) and inflammatory bowel disease (IBD), implying an important role of these cells in disease pathogenesis." (PMID 33488616, 2020). "The expansion of intermediate CD14+CD16+ monocytes has been reported in chronic inflammatory diseases including rheumatoid arthritis (RA)." (PMID 33488616, 2020). "MicroRNA expression profile of CD14+ monocytes from Rheumatoid Arthritis patients vs. CD14+ monocytes from healthy donors." (PMID 31169830, 2019). "It is overexpressed in macrophages resident in the membrane-lining layer and in CD14+ cells from synovial fluid of patients with rheumatoid arthritis (RA)." (PMID 30322050, 2018). "The number and frequency of CD14+CD3−CD19−CD56− monocytes/macrophages was markedly increased in the SFMCs of patients with gout compared to those of patients with rheumatoid arthritis (RA)." (PMID 29056937, 2017). "Increased numbers of pro-inflammatory CD14+CD16+ monocytes are found in chronic inflammatory disease states such as rheumatoid arthritis." (PMID 28494757, 2017). "Most groups have demonstrated an expansion of CD16+ monocytes in patients with rheumatoid arthritis with the recent delineation of CD16+ subpopulations strongly suggesting that CD14++CD16+ monocytes are the principle inflammatory effectors." (PMID 25852821, 2015). "CD14++CD16+ monocyte numbers are increased in various inflammatory conditions including rheumatoid arthritis and sarcoidosis." (PMID 26658828, 2015).
rheumatoid arthritis (continued). "The frequency of CD14++CD16+ monocytes is increased in rheumatoid arthritis and the frequency of both CD14+CD16++ and CD14++CD16+ is increased in type 2 diabetes and sarcoidosis." (PMID 26658828, 2015). "Several clinical studies have reported significantly elevated serum levels of CD14 under inflammatory conditions, such as Kawasaki disease, atopic dermatitis, rheumatoid arthritis, and systemic lupus erythematosus." (PMID 25668619, 2015). "In particular, LIGHT was reported to induce in vitro differentiation of OCs from peripheral blood (PB) CD14+ monocytes of healthy-donors, when co-cultured with nurse-like cells isolated from the synovium of patients with rheumatoid arthritis." (PMID 25460501, 2014). "Since PBMC contained a mixture of immune cells, we next focused on the DH-PS-induced effects on CD14+ cells which were reported to play a key role in rheumatoid arthritis." (PMID 24705413, 2014). "Beyond immunostimulation, alterations in circulating EV profiles offer clinically relevant biomarkers: in rheumatoid arthritis, CD14+ HLA-DR+ EVs reflect antigen-presenting-cell activation, and plasma RANKL+ EVs correlate with bone metastases and skeletal-related events." (PMID 41368630, 2025). "In addition, expression levels of Mpeg1, Enpp2, Tlr2, CD14, and Lyz2 were examined in the synovial tissues of patients with rheumatoid arthritis (RA) and persistent inflammatory, recurrent, and relapsing arthritis (PIRRA)." (PMID 40787440, 2025). "Another study detected increased TYRO3 expression by FACS analysis on the surface of pro-osteoclastogenic CD14+CD16− monocyte subpopulation in the blood of rheumatoid arthritis patients, indicating a role for TYRO3 in monocytic osteoclast precursor cells in the circulation." (PMID 38203403, 2023). "Clinical characteristics of the patients with rheumatoid arthritis used as a source of CD14+ cells." (PMID 36105797, 2022). "In untreated patients with rheumatoid arthritis, the detection of CD14++ CD16+ monocytes could predict the clinical response to methotrexate therapy." (PMID 34188092, 2021). "However, low level of CCR6 expression has been reported on myeloid blasts from the peripheral blood of AML patients, and on CD14+ monocytes from peripheral blood and synovial fluid of rheumatoid arthritis patients." (PMID 34277460, 2021). "We have demonstrate that the absolute number of circulating monocytes and their CD14+highCD16− and CD14+highCD16+ subsets have a predictive value for the clinical response to methotrexate treatment in untreated rheumatoid arthritis patients with high sensitivity and specificity." (PMID 25592233, 2015). "The CD14++CD16+ subset are expanded in patients with rheumatoid arthritis." (PMID 24650765, 2014). "The transcriptional profile of CD14+ cells from blood of 55 patients with rheumatoid arthritis (RA) was analysed with RNA-sequencing." (PMID 36105797, 2022). "In a rheumatoid arthritis (RA) study, a coculture of intermediate CD14++CD16+ Mos from arthritis patients with naïve T cells skewed the T cells toward pathogenic Th17 cells via the production of IL-23." (PMID 34360720, 2021). "A population of synovial inflammatory DCs (CD14+ infDCs; CD1c+CD14+CD16−) has been identified in inflamed SF samples of patients with rheumatoid arthritis (RA)." (PMID 32849606, 2020). "Synovial CD14+CD16+ monocytes have also been shown to be expanded in rheumatoid arthritis (RA) and osteoarthritis (OA) and to promote both Th1 and Th17 responses in vitro." (PMID 32787920, 2020). "Following injection of radiolabelled monocytes, radioactive CD14+ cells were detected in the intestine of patients with intestinal inflammation and in joints of patients suffering from rheumatoid arthritis (RA)." (PMID 31456804, 2019). "Total RNA was extracted from healthy control (HC, n = 10), SjS (n = 18), systemic lupus erythematosus (SLE, n = 10), and rheumatoid arthritis (RA, n = 10) peripheral blood CD14+ monocytes for miRNA microarray analysis." (PMID 27142093, 2016).
rheumatoid arthritis (continued). "We predicted miRNAs with regulatory impact on NFKB1 and TRAF6 gene expression and selected the miR-194-5p, miR-124-3p, miR-9-5p, and miR-340-5p and their target genes for expression analyses on CD14+ monocytes from rheumatoid arthritis (RA) patients and healthy controls." (PMID 39058384, 2024). "Contrarily, other studies have proven that OCLs are mainly derived from the classical CD14+CD16− monocyte population in healthy donors and patients with rheumatoid arthritis." (PMID 38338988, 2024). "Interestingly, paracrine ENO1 tends to activate the CD14-dependent TLR4 pathway via functionally binding with TLR4 on monocytes in rheumatoid arthritis (RA)." (PMID 36614179, 2023). "In rheumatoid arthritis, ENO-1 can be reattached to the cell surface of monocytes, which induces the CD14-dependent TLR4 signaling to stimulate their pro-inflammatory state." (PMID 38618493, 2023). "Then, we additionally compared the BR3+/CD14+ ratio among autoimmune diseases, such as systemic lupus erythematosus (SLE) and rheumatoid arthritis (RA)." (PMID 32576236, 2020). "As the indirect antigen presenting cells and co-stimulatory signaling transducer, CD14+ monocytes induced the activation and differentiation of CD4+ T cells in rheumatoid arthritis, lung squamous carcinoma, and chronic hepatitis C." (PMID 32276581, 2020). "The frequency of intermediate monocytes (CD14+, CD16+) is increased in the blood of patients with inflammatory diseases, such as rheumatoid arthritis or leishmaniasis." (PMID 32269570, 2020). "It has been demonstrated that CD14+CD16+ intermediate monocytes are induced by IL-10 and positively correlate with disease activity in rheumatoid arthritis (RA)." (PMID 33488616, 2020). "The double-positive CD14+CD16+-MΦ subset frequency increases in systemic inflammation and inflammatory diseases such as rheumatoid arthritis (RA), Crohn’s disease, Eales’ disease and asthma." (PMID 30658702, 2019). "Previous studies have shown that the number of CD14+CD16+ monocytes are expanded during severe infectious and inflammatory conditions, such as Rheumatoid arthritis (RA), tuberculosis, asthma and sarcoidosis." (PMID 25689051, 2015). "In the literature, LIGHT was reported in rheumatoid arthritis erosive bone-disease as expressed by synovial CD4+ T-cells as well as PB and synovial fluid CD14+ monocytes and CD20+ B-cells." (PMID 25460501, 2014). "TLR4 and CD14 SNPs may qualitatively and/or quantitatively alter the expression, affecting the susceptibility and severity of systemic lupus erythematosus (SLE) and rheumatoid arthritis (RA)." (PMID 37176151, 2023). "In contrast to these three major monocyte subsets, the function of the newly identified human CD14+CD56+ monocytes remains undefined, despite increased number of these cells found in certain pathological conditions, such as Crohn’s disease and rheumatoid arthritis." (PMID 33995378, 2021). "A number of studies have shown that CD14+CD16+ monocytes are expanded in peripheral blood and inflamed tissues during acute and chronic inflammation such as is seen with inflammatory bowel disease (IBD) and rheumatoid arthritis (RA)." (PMID 33488616, 2020). "The role of CD14 polymorphisms in autoimmune disorders has been widely explored, including inflammatory bowel disease (IBD), multiple sclerosis (MS), rheumatoid arthritis (RA), juvenile idiopathic arthritis, systemic lupus erythematosus, and type 1 diabetes mellitus (T1DM)." (PMID 30700980, 2018). "Elevated levels of soluble CD14 have been found in non-infectious and infectious diseases such as polytraumatised and severely burned patients, rheumatoid arthritis." (PMID 28936284, 2017). "In rheumatoid arthritis (RA), CD64 is evaluated by overexpression of CD14++CD16- and CD14++CD16+ monocytes and correlates with the risk of disease activation." (PMID 39816386, 2024).
rheumatoid arthritis (continued). "CD14+CD16- classical monocytes/macrophages were lower in PsA SF than in the SF of patients with rheumatoid arthritis (RA), while CD14+CD16+ intermediate monocytes/macrophages were more predominant in PsA SF compared to RA SF." (PMID 35837394, 2022). "However, elevated expression of miR-223 in CD68+ macrophages, CD14+ monocytes, and CD4+ T cells from synovium of rheumatoid arthritis (RA) patients was reported." (PMID 34222229, 2021). "Interestingly, paracrine ENO1 tends to activate the CD14-dependent TLR4 pathway via functionally binding with TLR4 on monocytes by a dual mechanism, initially pro-inflammatory and later anti-inflammatory, in rheumatoid arthritis (RA)." (PMID 36614179, 2023). "Interestingly, decreases in CD14++CD16- monocytes correlate with a positive prognostic response for patients, but whether this is because they contribute directly to disease progression or the inflammatory tone of rheumatoid arthritis is not known." (PMID 26766566, 2016).
breast cancer (72 papers, 2009 to 2025). A primary or metastatic malignant neoplasm involving the breast. "CD1c+CD14+ DC3 frequency is positively associated with the presence of tissue-resident memory CD8+ T cells in Luminal A-type breast cancer." (PMID 40584260, 2025). "cDCs as well as pDCs have been found to be beneficial for anti–tumor responses to breast cancer, while CD14+ cells are associated with immunosuppression across cancer types." (PMID 39211033, 2024). "Accordingly, two studies with breast cancer patients demonstrated a reduced expression of HLA-DR in CD14+ cells associated with mechanisms of immunosuppression." (PMID 38793599, 2024). "Additional CD14+ CD16+ monocytes were associated with an increased risk of breast cancer (OR = 1.000, 95% CI: 1.000–1.001, p = 0.005)." (PMID 38826800, 2024). "Monocyte counts have previously been associated with CTC levels in MBC patients and high levels of CD14+HLA-DR+ monocytes associated with improved breast-cancer-specific survival in MBC patients treated with high-dose chemotherapy." (PMID 35626676, 2022). "In fact, we show here that up-regulation of the mRNA expression levels of PD-L1, FOXP3, CD80, CD40, and CD14 in PBMCs is associated with breast cancer." (PMID 26942414, 2017). "In conclusion, our data showed that the mRNA expression levels of PD-L1, FOXP3, CD80, CD40, and CD14 in PBMCs were associated with breast cancer burden." (PMID 26942414, 2017). "Likewise, “HLA DR on CD33br HLA DR+ CD14‐” mediated the causal relationship between Species Prevotellamassilia and breast cancer, having a mediating ratio of 7.89%." (PMID 39654239, 2024). "Additionally, HLA DR on CD33br HLA DR+ CD14‐ was identified as a mediator in the causal relationship between Species Prevotellamassilia and breast cancer." (PMID 39654239, 2024). "We found that it may be associated with HLA DR on CD33br HLA DR+ CD14‐ cells in the development of breast cancer.CD33br HLA DR+ CD14‐ cells might be a kind of cell possessing certain antigen-presenting ability." (PMID 39654239, 2024). "Moreover, in luminal A breast cancer patients, advanced disease was associated with a shift towards higher representation of intermediate (CD14+ CD16 +) over classical (CD14hi CD16−) monocytes, reflecting the lack of immunosuppression associated with this subtype." (PMID 33804027, 2021). "Higher levels of expression of FcεRI, or CD14, or of both combined, associated with better recurrence-free survival (RFS) and OS (10 years) in HER2+ breast cancer." (PMID 40074330, 2025). "For instance, in breast cancer, the transcriptional profiles of infiltrating CD1c+CD14+ DCs and other DC populations were extensively studied, revealing their subset-specific adaptation to the TMEs of different breast cancer types." (PMID 40584260, 2025). "Regarding ROS production, CBD has been shown to disrupt mitochondrial integrity and induce ROS production and apoptosis in human CD14+ monocytes, breast cancer cells, and GBM cells." (PMID 40871052, 2025). "The levels of Lipopolysaccharide-binding protein (LBP) and soluble CD14 (sCD14) serve as markers for bacterial translocation, indicating the potential existence of a gut-breast cancer microbiota axis." (PMID 38521934, 2024). "As TREM2+ macrophages are infiltrating in nature during cancer development and transcriptionally proximal to CD14+ CCR2+ monocytes in breast cancer, they are concluded as HSC-derived recruited macrophages." (PMID 39104525, 2024). "Conditioned supernatants from breast cancer (MCF-7) cells were used as a source of tumor-specific secreted factors to differentiate CD14+ monocytes into TAMs." (PMID 36960065, 2023). "For macrophages, the level of infiltration of CD14-positive macrophages can serve as an indicator of early recurrence of breast cancer." (PMID 36479102, 2022).